CDKN2B (cyclin dependent kinase inhibitor 2B)
Diseases named in the same sentence as CDKN2B in open-access papers (continued):
Sharing a sentence is not in itself a finding about the gene and the disease.
lymphoid leukemia (1 paper, 2022). A malignant lymphocytic neoplasm of B-cell or T-cell lineage involving primarily the bone marrow and the peripheral blood. "The reduced proliferation of Vav3-deficient lymphoid leukemia B-cell progenitors is associated with increased expression of at least Cdkn2a and Cdkn2b, genes known to be regulated by PRC." (PMID 35650206, 2022).
malignant glioma (1 paper, 2019). A grade III or grade IV glioma arising from the central nervous system. "As a CNV-driven ceRNA, CDKN2B has been reported to serve as a functional unit in the oncogenesis of malignant gliomas, its ceRNA pairs, CDK2 and RBL1, were also annotated in cell cycle and located in the downstream of the pathway." (PMID 31719831, 2019).
melanocytic neoplasm (1 paper, 2024).
metastatic tumors (1 paper, 2022). "The mutational frequencies of CDKN2B (14.8% vs. 0%, p = 0.001), FAT3 (7.4% vs. 0%, p = 0.041), MTAP (13% vs. 1.6%, p = 0.023), and SMAD4 (31.4% vs. 15.6%, p = 0.049) in metastatic tumors were significantly higher than that in primary tumors." (PMID 35664782, 2022). "Importantly, the mutational frequency of CDKN2B (14.8% vs. 0%, p = 0.001), FAT3 (7.4% vs. 0%, p = 0.041), MTAP (13% vs. 1.6%, p = 0.023), and SMAD4 (31.4% vs. 15.6%, p = 0.049) in metastatic tumors were significantly higher than those in primary tumors." (PMID 35664782, 2022). "The mutational frequencies (metastatic vs. primary) of CDKN2B (14.8% vs. 0%, p = 0.001), FAT3 (7.4% vs. 0%, p = 0.041), MTAP (13% vs. 1.6%, p = 0.023), and SMAD4 (31.4% vs. 15.6%, p = 0.049) in metastatic tumors were significantly higher than in primary tumors." (PMID 35664782, 2022). "Notably, CDKN2B and FAT3 alterations occurred only in metastatic tumors." (PMID 35664782, 2022). "Notably, CDKN2B and FAT3 alterations occurred only in patients with metastatic tumors." (PMID 35664782, 2022).
microphthalmia (1 paper, 2024). Congenital or developmental anomaly in which the eyeballs are abnormally small. "Overexpression of Cdkn2b in Xenopus microphthalmia models correlated with reduced cell proliferation due to cell cycle misregulation, and upregulation of CDKN2A and CDKN2B reduces proliferation in the developing retina." (PMID 38821055, 2024).
mucinous carcinomas (1 paper, 2023).
mucoepidermoid carcinoma (1 paper, 2023). A carcinoma morphologically characterized the presence of cuboidal mucous cells, goblet-like mucous cells, squamoid cells, cystic changes, and a fibrotic stromal formation. "CDKN2A and CDKN2B GA were common in mucoepidermoid carcinoma (MECa) (52.5 and 30.5%)." (PMID 36831055, 2023).
myeloid neoplasm (1 paper, 2019). Proliferation of myeloid cells originating from a primitive stem cell. "Genes associated with methylation and myeloid neoplasms, including DNMT3A and NRAS, were more commonly mutated in T-ALL with CDKN2B hypermethylation." (PMID 30635552, 2019).
oligodendroglial tumor (1 paper, 2016). Oligodendrogliomas are cerebral tumors that are differentiated from other gliomas on the basis of their unique genetic characteristics and better response to chemotherapy. "In accordance with previous studies, high methylation rates were found for CDKN2A 17, CDKN2B 18, and RASSF1A 8, suggesting that aberrant methylation of these genes may indicate early change in tumorigenesis of oligodendroglial tumors, regardless of cell type." (PMID 27367901, 2016).
oral cancer (1 paper, 2021). "Reduced expression of CDKN2B was determined as a marker of disease recurrence in oral cancer." (PMID 34944712, 2021).
osteoporosis (1 paper, 2019). A condition of reduced bone mass, with decreased cortical thickness and a decrease in the number and size of the trabeculae of cancellous bone (but normal chemical composition), resulting in increased fracture incidence. "The results implied that mRNA CDKN2B,CIDEC,and THBS4 may play key roles in osteoporosis process and development." (PMID 31164921, 2019).
parathyroid adenomas (1 paper, 2017). "The relative expressions of the CDKN2A, CDKN2B and RASSF1A genes were analysed by quantitative RT-PCR and were related to the cyclin D1 (CCND1) expression in parathyroid adenoma samples." (PMID 28600574, 2017). "Gene expressions of cyclin D1 (CCND1) and regulatory molecules (CDKN2A, CDKN2B and RASSF1A) was analysed in parathyroid adenoma tissues (n = 30)." (PMID 28600574, 2017). "Our study confirms the methylation-mediated transcriptional silencing of both CDKN2A and CDKN2B, and is the first study to demonstrate that the hypermethylation of CDKN2B is almost equivalent to CDKN2A in parathyroid adenomas." (PMID 28600574, 2017). "In the present study we analysed the expression patterns of three potential tumor suppressor genes, CDKN2A, CDKN2B and RASSF1A, in sporadic parathyroid adenomas." (PMID 28600574, 2017). "In this study we found that the promoter region of the three genes (CDKN2A, CDKN2B and RASSF1A) examined in sporadic parathyroid adenomas is frequently hypermethylated with the resultant reduced expression of their respective gene products." (PMID 28600574, 2017). "In conclusion, reduced expression of CDKN2A, CDKN2B and RASSF1A with significant hypermethylation of promoter region of these genes and inactivation of these genes through epigenetic regulation may be important factor in tumorigenesis in substantial proportion of parathyroid adenomas." (PMID 28600574, 2017).
parotid tumors (1 paper, 2025). "A first case, was a chemotherapy-refractory, CDKN2B-deleted metastatic parotid tumors, that received abemaciclib as fourth-line therapy." (PMID 39177668, 2025).
penile carcinoma (1 paper, 2022). "That finding is interesting because loss of CDKN2B was described in penile carcinomas." (PMID 36564761, 2022).
peripheral arterial disease (1 paper, 2014). A disorder of the arteries supplying the upper and lower extremity and the visceral organs. "Recently, a common variant near the CDKN2B gene in the chromosome 9p21 locus is associated with a lower ankle-brachial index which is a simple and reliable method to detect peripheral arterial disease." (PMID 24625579, 2014).
pituitary tumours (1 paper, 2016). "Studies of other mouse models deleted for genes that were not previously known to be associated with the development of pituitary tumours in man have revealed roles for such genes, which includes Rb, Cdkn2b, Drd2, Prl and Prlr, in pituitary tumourigenesis." (PMID 26320859, 2016). "To date, homologous deletions of 10 different genes, which are Men1, Cdkn1b, Prkar1a, Rb, Cdkn2b (encoding p19), Drd2, Cdkn2c (encoding p18), Aip, Prl and Prlr, have been reported to yield mouse knockout models for pituitary tumours." (PMID 26320859, 2016).
Primary glaucoma (1 paper, 2021). "The association of CDKN2B (rs3217992, rs1063192) and CDKN2B-AS1 (rs2157719, rs4977756) gene polymorphisms with primary glaucoma cases was investigated in a total of 910 samples: 449 controls having cataract, 313 POAG cases and 148 PACG cases." (PMID 33397358, 2021).
salivary gland carcinoma (1 paper, 2024). A carcinoma that arises from the major or minor salivary glands. "CDKN2A/B CDKN2B loss has been associated with high-grade salivary gland carcinomas and was also positive in our case." (PMID 39329865, 2024).
schwannomatosis (1 paper, 2022). The least frequent form of the rare genetic disorder neurofibromatosis. "Screening of the coding region of DGCR8, COQ6, CDKN2A, and CDKN2B was carried out, based on previous reports that point to these genes as potential candidate genes for schwannomatosis." (PMID 35723634, 2022).
serous ovarian cancer (1 paper, 2015). "The most frequently hypermethylated genes in stromal progenitor cells from ascites and corresponding bulk tumor tissues from the patients with serous ovarian cancer at an advanced stage were CDKN2B, RASSFIA, DLC1, and CCND2." (PMID 26597084, 2015).
Skin tumours (1 paper, 2019). "Skin tumours develop in a small fraction (10%) of Cdkn2a knockout mice hemizygous for Cdkn2b, however, with a much longer latency than full Cdkn2ab knockout mice." (PMID 30926782, 2019).
thymic carcinoma (1 paper, 2023). Thymic carcinoma (TC) is a type of thymic epithelial neoplasm characterized by a high malignant potential. "We observed focal deletions of the CDKN2A and CDKN2B loci in thymic carcinomas and B3 thymomas." (PMID 38201593, 2023).
venous thromboembolism (1 paper, 2022). Occlusion of the lumen of a vein by a thrombus that has migrated from a distal site via the blood stream. "Somatic tumor mutations in STK11, KRAS, CTNNB1, KEAP1, CDKN2B and MET, which were reported to be associated with cancer-induced venous thromboembolism in an independent study, were infrequent in OSCC." (PMID 35053621, 2022).
ZIKV infection (1 paper, 2018). "Selected genes blocking cell growth (DDIT3, GADD45B, and CDKN2B) were significantly upregulated by ZIKV infection." (PMID 30228241, 2018).
tumor (345 papers, 1997 to 2026). "The CDKN2A and CDKN2B are tumor-suppressor genes which encodes the Alternate Reading Frame (ARF) protein." (PMID 38593544, 2024). "CDKN2A and CDKN2B are tumor suppressor genes located at 9p21, and their deletion inevitably increases tumor risk." (PMID 38756785, 2024). "Cdkn2b is often inactivated due to deletion, methylation, or mutation in various tumors, leading to tumor progression and being considered an inhibitor of tumors." (PMID 39364045, 2024). "CDKN2B, encoding cyclin-dependent kinase inhibitor 2B (p15), is a tumor-suppressor gene located on chromosome 9p21." (PMID 37325482, 2023). "The proteins that are encoded by CDKN2A (p16INK4A and p14ARF) and CDKN2B (p15INK4B) regulate the cell cycle and apoptosis and thus play the role of the tumor suppressor." (PMID 37908227, 2023). "The variant rs3731198 is located in the CDKN2A/CDKN2B gene region, which is an important tumor suppressor gene involved in cell cycle regulation." (PMID 36233401, 2022). "Next-generation sequencing identified amplification of TERT and loss of CDKN2A/CDKN2B in the primary tumor." (PMID 34127009, 2021). "In GC, upregulated E2F1 expression, targeting the TINCR/STAU1/CDKN2B signaling axis, was positively associated with poor prognosis due to its association with advanced stage and larger tumor size." (PMID 34532281, 2021). "Loss of CDKN2A/CDKN2B genes in tumor Schwann cells first leads to development of premalignant, atypical neurofibromatosis neoplasms of uncertain biological potential (ANNUBP)." (PMID 33863389, 2021). "Our findings revealed that miR-29b has tumor suppressor activity linked to enhanced expression of the cell cycle inhibitor CDKN2B via suppression of the DNA methyltransferase DNMT3B." (PMID 33601338, 2021). "In contrast, amplification of telomerase reverse transcriptase (TERT) and loss of Cyclin Dependent Kinases Inhibitors (CDKN); CDKN2A/CDKN2B were detected in the tumor." (PMID 34127009, 2021). "Mutations in PTCH1 and CDKN2B were validated using ddPCR in the tumour/normal DNA and the CSF and plasma cfDNA." (PMID 33110059, 2020). "As expected, in PDCX-ZEC145 models with CDKN2A and CDKN2B loss, palbociclib given at a 75 mg/kg dose demonstrated a remarkable inhibition of tumor growth." (PMID 31700061, 2019). "Loss of CDKN2A-encoded p16 leads to tumor promoting growth properties; in contrast, the consequence of loss of CDKN2B-encoded p15 and its relationship with tumorigenesis is less clear." (PMID 29464040, 2018). "These events reinforce the previous illustration in GBM that hypermethylation and deletion of RB1 and CDKN2B respectively contribute to the loss of tumor suppressor function." (PMID 30059495, 2018). "The proteins encoded by CDKN2A and CDKN2B are tumor suppressors with well-established roles in cell proliferation, apoptosis, senescence and aging." (PMID 30087655, 2018). "The CDKN2A and adjacent cyclin-dependent kinase inhibitor 2B (CDKN2B) loci encode three distinct tumor suppressors: p16 INK4A, p14 ARF, and p15 INK4B." (PMID 29069809, 2017). "Loss of CDKN2A/CDKN2B or PTPRD tumor suppressor was often used to explain the frequent chromosome 9p deletion in human cancer." (PMID 28977839, 2017). "The inhibition of the Ink4/Arf locus, which contains Cdkn2a and Cdkn2b encoding three powerful tumor suppressors, p16( Ink4a ), p19 ( Arf ), and p15 (Ink4b ), is one of the key characteristics of pluripotent stemcells." (PMID 22708059, 2012). "Reduced gene dosage across 9p21.3 was associated with increased tumor thickness, mitotic rate, and ulceration (P = 0.02, 0.02, and 0.002, respectively), specifically in coding regions impacting on CDKN2B and P14ARF and CDKN2A." (PMID 20140953, 2010). "Similarly, the concurrent loss of CDKN2A and CDKN2B, which encode critical cell cycle regulators, contributes to uncontrolled cell division and tumor progression." (PMID 40223032, 2025). "Mutations in CDKN2A and CDKN2B can lead to uncontrolled cell proliferation and even tumor growth." (PMID 40535548, 2025).
tumor (continued). "It has been previously shown that long-term OE of the inflammation-related pathway Ink4/Arf locus, comprising Cdkn2a-Cdkn2b genes that encode four potent tumor suppressors, namely p16Ink4a, p19Arfand, p15Ink4b, and p21Cdkn1a, inhibited the efficiency of in vitro reprogramming." (PMID 35947961, 2022). "CDKN2A and CDKN2B encode three well-established tumor suppressors: p15, p16, and p14ARF." (PMID 35626065, 2022). "Another gene showing promoter hypermethylation in pulmonary carcinoids is CDKN2B, coding for a cyclin-dependent kinase inhibitor p15Ink4b which is functionally similar to the tumor-suppressor gene CDKN2A (encoding for the p16INK4a protein), but less well characterized in its tumorigenic potential." (PMID 33641055, 2021). "Amplification of TERT and loss of CDKN2A/CDKN2B detected in the tumor by next gene sequencing suggests that they may play an important role in this case." (PMID 34127009, 2021). "Amplification of Telomerase reverse transcriptase (TERT) and loss of cyclin dependent kinase inhibitor 2A/2B (CDKN2A/CDKN2B) detected in the tumor by next gene sequencing suggests that they may play an important role in this case." (PMID 34127009, 2021). "Homozygous loss of CDKN2A/CDKN2B locus at chromosome 9p21.3 was identified in one tumor." (PMID 32726920, 2020). "Therefore, loss of CDK4 results in cell cycle arrest and tumor cell senescence, while loss of CDKN2B maintains cell cycle progression and tumor cell growth." (PMID 29383146, 2017). "This region encodes the CDKN2A and CDKN2B tumor suppressor genes, and may be deleted in several tumor types." (PMID 25314013, 2014). "However, ulceration of the tumor was most significantly associated with reduced gene dosage at CDKN2B (one sided test P = 0.006, two sided P = 0.01) and regions coding for P14ARF (one sided P = 0.002, two sided P = 0.004)." (PMID 20140953, 2010). "Loss of SRC-1 expression dramatically increased tumor latency in this model, which correlated with decreased proliferation index and upregulation of cell cycle inhibitors such as transforming growth factor β2 (5.2 fold), Cdkn1a (8.8 fold), and Cdkn2b (8.5 fold)." (PMID 21080969, 2010). "Homozygous loss of the 9p21 locus encompassing CDKN2A, CDKN2B, and MTAP is the most frequent copy number alteration across tumor types, making it a promising target for precision medicine strategies." (PMID 42000949, 2026). "CDKN2A (which includes the p16/IKN4A and p14/ARF proteins) and CDKN2B (INK4B) are well-known tumor suppressors." (PMID 40378113, 2025). "CDKN2A (p16/Ink4a) and CDKN2B (p15/Ink4b) inhibit cyclin-dependent kinases and are important tumor suppressors." (PMID 39319854, 2025). "The cyclin-dependent kinase inhibitor 2A (CDKN2A) gene and the cyclin-dependent kinase inhibitor 2B (CDKN2B) gene are two adjacent tumor suppressor genes that are collectively referred to as the CDKN2A/B." (PMID 40017529, 2025). "This study explored how DNA methylation in CTVT gene promoters, particularly MYC (oncogenic) and CDKN2B (tumor suppressor), affects gene and protein expression." (PMID 39185058, 2024). "This differentiation between high and low PS score groups underscores the possible tumour‐suppressive role of certain cell cycle‐related genes, like CDKN2B, aligning with existing literature that identifies CDKN2B as a tumour‐suppressor gene." (PMID 38751024, 2024). "Read coverage at the CDKN2A and CDKN2B loci showed that tumor samples had relatively lower coverage, as compared to the normal samples, supporting shallow deletions." (PMID 39122888, 2024).